DUXAP10 (double homeobox A pseudogene 10 )
Synonyms: LNMAT1
Gene: Long non-coding RNA gene on chromosome 14 (19,268,701 to 19,337,756, reverse strand). Ensembl gene ENSG00000292986.
Diseases named in the same sentence as DUXAP10 in open-access papers:
DUXAP10 is named in the same sentence as 27 diseases in open-access papers, as found by Europe PMC text mining. Sharing a sentence is not in itself a finding about the gene and the disease. The quoted sentences say what the papers report.
bladder cancer (6 papers, 2018 to 2025). "The knockdown of DUXAP10 was found to inhibit bladder cancer cell proliferation, induce cell cycle arrest at the G0/G1 phase, and promote apoptosis." (PMID 37627900, 2023). "The expression of DUXAP10 in bladder cancer cell lines (5637, EJ, RT4, T24, TCCSUP, and UMUC3) was significantly higher as compared to that of SV-HUC-1 cell line, thus suggesting that DUXAP10 is overexpressed in bladder cancer." (PMID 37627900, 2023). "Taken together, DUXAP10 plays an important role in bladder cancer and the inhibition of DUXAP10 is a potential therapeutic target for bladder cancer." (PMID 37627900, 2023). "Subsequently, one of these altered pseudogenes termed DUXAP10 is frequently overexpressed in multiple cancers including liver hepatocellular carcinoma, bladder cancer, esophageal Cancer, and gastric cancer tissues." (PMID 29374493, 2018). "DUXAP10 is the only pseudogene significantly overexpressed across all four GEO datasets and is frequently upregulated in multiple cancers, including liver hepatocellular carcinoma, bladder cancer, and esophageal cancer." (PMID 40556338, 2025). "In addition, the knockdown of DUXAP10 also inhibited the PI3K/Akt/mTOR signaling pathway in bladder cancer cells." (PMID 37627900, 2023). "The pesudogene DUXAP10 is the only pseudogene that significantly over-expressed in all four GEO datasets, and frequently over-expressed in many other cancers including Liver Hepatocellular carcinoma, Bladder cancer, and Esophageal Cancer." (PMID 29374493, 2018). "Previous studies have shown that DUXAP10 could promote tumor progression in non-small cell lung cancer, colorectal cancer, gastric cancer, pancreatic cancer, esophageal squamous cell carcinoma, and bladder cancer." (PMID 36053455, 2022).
colorectal cancer (5 papers, 2017 to 2022). A primary or metastatic malignant neoplasm that affects the colon or rectum. "Over the past decade, DUXAP10 was highly expressed in colorectal cancer (CRC) tissues and HCT116, SW620, and SW480 cell lines." (PMID 35186937, 2022). "Next, to detect the distribution of DUXAP10 in colorectal cancer cells, we fractionated CRC cell lines into nuclear and cytoplasmic fractions, thoroughly separaing the nucleus from the cytoplasm." (PMID 28779166, 2017). "DUXAP10,a pseudogene derived long non-coding RNA(lncRNA), is overexpression in colorectal cancer (CRC), but its expression pattern, biological function and underlying mechanism in CRC is still undetermined." (PMID 28779166, 2017). "In the present study, we revealed that pseudogene derived lncRNA DUXAP10 is upregulated in colorectal cancer tissues and DUXAP10 expression was significantly higher in patients with a larger tumor size, a higher pathological stage and lymph node metastasis." (PMID 28779166, 2017). "To further investigated whether the effect of DUXAP10 on colorectal cancer cells proliferation reflected cell apoptosis, we performed flow cytometry and Tunel staining assays." (PMID 28779166, 2017). "We demonstrated that DUXAP10 which is associated with the RNA binding protein LSD1 to inhibit p21 and PTEN expression plays a critical role in the proliferation and tumorigenicity of colorectal cancer cells." (PMID 28779166, 2017). "Our results indicated that silencing DUXAP10 expression could suppress colorectal cancer cells tumor growth in vivo." (PMID 28779166, 2017). "Interestingly, we further analyzed the expression level of DUXAP10 in 20 types of cancer tissues and normal tissues samples from TCGA and found that DUXAP10 is overexpressed in multiple cancers, such as Colorectal cancer, Thyroid cancer, and Uterine Corpus Endometrial Carcinoma, Pancreas cancer." (PMID 29374493, 2018). "Therefore, we speculate that DUXAP10 expression may correlate with the malignant behaviors of colorectal carcinoma." (PMID 28779166, 2017). "Like the pseudogene-derived long non-coding RNA DUXAP10, can bind to histone demethylase lysine-specific demethylase 1 and silence the expression of p21 and phosphatase and tensin homolog (PTEN), then promote colorectal cancer cell growth." (PMID 30286715, 2018). "To validate the analysis finding, we detected DUXAP10 expression in an cohort of 58 pair colorectal cancer and normal tissues using qPCR." (PMID 28779166, 2017). "Moreover, analysis of TCGA colorectal cancer and normal tissues RNA sequencing data showed that DUXAP10 expression is upregulated in tumor tissues compared with normal tissues." (PMID 28779166, 2017).
non-small cell lung carcinoma (5 papers, 2017 to 2022). A group of at least three distinct histological types of lung cancer, including non-small cell squamous cell carcinoma, adenocarcinoma, and large cell carcinoma. "Functional and mechanistic experiments suggested that DUXAP10 exerted oncogenic roles in non-small cell lung cancer by binding to LSD1 and epigenetic silencing expression of LATS2 and RRAD." (PMID 32185172, 2020). "It has been reported that DUXAP10 is significantly increased in non-small cell lung cancer tissues and knockdown of DUXAP10 could inhibit the inhibited non-small cell lung cancer cell migration and invasion." (PMID 30996112, 2019). "Moreover, the cell proliferation, migration, and invasion in non-small cell lung cancer cells are significantly up-regulated in the DUXAP10 overexpression cell model." (PMID 30996112, 2019). "Previous studies found that DUXAP10 was upregulated in non small cell lung cancer (NSCLC) and could promote cancer cell proliferation and invasion." (PMID 28779166, 2017). "The in vivo study showed that knockdown DUXAP10 could impair non-small cell lung cancer growth." (PMID 30996112, 2019).
gastric cancer (4 papers, 2018 to 2022). A primary or metastatic malignant neoplasm involving the stomach. "Moreover, results from DUXAP10 loss-and-gain-of-function assays illustrated that DUXAP10 overexpression is in line with gastric cancer patients’ poor prognosis." (PMID 30996112, 2019). "Moreover, higher DUXAP10 expression is significantly associated with gastric cancer patients poorer prognosis and shorter survival time." (PMID 29374493, 2018). "Knockdown of DUXAP10 significantly decreased the proliferation, migration, and invasion of cells in gastric cancer." (PMID 30996112, 2019). "DUXAP10 was found to be overexpressed in bladder cancer, esophageal cancer, gastric cancer, liver HCC, and colorectal cancer." (PMID 30996112, 2019). "The results showed that DUXAP10 is significantly up-regulated in 50/68 samples (Fold change> 1.5), and 6 gastric cancer cell lines." (PMID 29374493, 2018). "The results revealed that decreased DUXAP10 impeded the gastric cancer cells migration and invasion compared with controls." (PMID 29374493, 2018). "Moreover, our previous study revealed that pseudogene DUXAP10 is over-expressed in gastric cancer, and promoted cell proliferation and invasion via interacting with EZH2 and LSD1 to repress LATS1 transcription." (PMID 34660601, 2021). "Moreover, multivariate Cox regression analyses showed that expression of DUXAP10 (p = 0.034), along with TNM stage (P = 0.013), was an independent prognostic factor for gastric cancer patients." (PMID 29374493, 2018).
pancreatic cancer (4 papers, 2018 to 2022). "Double homeobox A pseudogene 10 (DUXAP10)-derived lncRNA also plays an important role in pancreatic cancer cells." (PMID 35327654, 2022). "Thus, LSD1 seems to play an important role in pancreatic cancer cell proliferation as it binds to DUXAP10." (PMID 35327654, 2022).
hepatocellular carcinoma (3 papers, 2019 to 2022). A malignant tumor that arises from hepatocytes. "The long non-coding RNA DUXAP10 has been involved in the development, progression, and metastasis in several human cancers, but its biological function and underlying mechanism in hepatocellular carcinoma (HCC) still undetermined." (PMID 30996112, 2019).
lymph node metastasis (3 papers, 2017 to 2022). "DUXAP10 was also found to be positively correlated with advanced pathological stages, larger tumor sizes, lymph node metastasis, and poor prognosis." (PMID 35186937, 2022). "By univariate survival analysis, tumor size, lymph node metastasis, TNM stage and DUXAP10 expression level can be used as prognostic factors." (PMID 28029651, 2017). "Moreover, multivariate Cox regression analyses showed that expression of DUXAP10 (p=0.013), along with TNM stage (P=0.023) and lymph node metastasis(p=0.029), were independent prognostic factors for NSCLC patients." (PMID 28029651, 2017). "In addition, DUXAP10 overexpression was positively correlated with the adverse clinicopathological features and aggressive outcomes of several cancer types, including tumor size, TNM staging, histological grading, lymph node metastasis, and survival rates." (PMID 35186937, 2022). "Moreover, univariate survival analysis showed that lymph node metastasis, TNM stage and DUXAP10 expression level could be viewed as prognostic factors." (PMID 29374493, 2018).
ovarian carcinoma (3 papers, 2018 to 2022). A malignant neoplasm originating from the surface ovarian epithelium. "Clinical data analysis showed that the overall survival of patients with ovarian cancer whose DUXAP10 was overexpressed was significantly lower than that in the DUXAP10 low expression group." (PMID 29921308, 2018). "The expression of lncRNA DUXAP10 in ovarian cancer tissues was significantly higher than that in normal ovarian tissues." (PMID 29921308, 2018).
breast carcinoma (2 papers, 2017 to 2018). "To further explore the underlying target genes of DUXAP10 in GC cells, we analyzed previously published gene expression profile downstream of LSD1 in breast cancer cells and other known LSD1 and PRC2 targets." (PMID 29374493, 2018). "To further explore the underlying target genes of DUXAP10 in NSCLC cells, we analyzed previously published gene expression profile downstream of LSD1 in breast cancer cells and other known LSD1 targets." (PMID 28029651, 2017).
glioma (2 papers, 2022). A benign or malignant brain and spinal cord tumor that arises from glial cells (astrocytes, oligodendrocytes, ependymal cells). "It was also found that DUXAP10 promotes the stemness of glioma U251 and T98G cells by binding to HuR and thus upregulating the expression of Sox12." (PMID 35186937, 2022). "DUXAP10 has been indicated to be highly expressed in glioma cell lines (HS683, U251, U373, U87, T98G LN-319, and SW1783 cells) and tissues gained from patients under surgery at the First Affiliated Hospital of Jinan University." (PMID 35186937, 2022). "Previous study had proved that HuR can not only bind to DUXAP10 but also SOX12 in glioma cells." (PMID 36053455, 2022). "Mounting evidence indicates that DUXAP10 is abnormally highly expressed in a variety of cancers, including HCC, lung cancer, glioma, RCC, PTC, PCa, CML, OC, GC, PC, BC, CRC, and ESCC." (PMID 35186937, 2022). "DUXAP10 knockdown remarkably reduced the activity of ALDH and the expression of stemness markers (Sox2, CD133, Oct4) in glioma cells." (PMID 35186937, 2022). "Several studies have reported that DUXAP10 is aberrantly expressed in numerous human cancers, such as HCC, BC, NSCLC, glioma, RCC, PTC, PCa, CML, OC, PC, GC, CRC, ESCC, and OSCC." (PMID 35186937, 2022). "An increasing number of oncology studies have reported that the overexpression of DUXAP10 in diverse tumor tissues (such as NSCLC, glioma, and ESCC) could be used to distinguish normal from tumor tissues, making it highly promising for the early diagnosis of tumors." (PMID 35186937, 2022).
lung carcinoma (2 papers, 2022). "A high level of DUXAP10 expression in lung cancer patients was linked to not only lower OS and relapse-free survival (RFS) rates but also larger tumor sizes, advanced tumor stages, lymph node metastasis, and even poor prognosis." (PMID 35186937, 2022).
oral squamous cell carcinoma (2 papers, 2021 to 2022). "A double homeobox A pseudogene 10 (DUXAP10) can be used as a marker in both oral squamous cell carcinoma (OSCC) and ESCC." (PMID 34947885, 2021).
thyroid cancer (2 papers, 2018 to 2025). "High DUXAP10 expression was significantly associated with decreased overall survival in thyroid cancer patients." (PMID 41375055, 2025).
anaplastic thyroid cancer (1 paper, 2025). "We found that reducing the expression of a single long non-coding RNA, DUXAP10, significantly diminished multiple cancer-associated phenotypes of anaplastic thyroid cancer." (PMID 41375055, 2025).
chronic myelogenous leukemia (1 paper, 2022). "DUXAP10 was upregulated in chronic myelogenous leukemia (CML) THP-1, KG-1, and K562 cells, and its expression level was observed to gradually increase in response to clinical upstaging of CML (chronic phase, acceleration phase, and blast phase)." (PMID 35186937, 2022).
diabetes (1 paper, 2017). "To further verify this result, we conducted western blot analysis and revealed that Ras-related associated with diabetes (RRAD) and Large tumor suppressor 2 (LATS2) protein levels was also increased in si-DUXAP10 transfected cells." (PMID 28029651, 2017).
lung adenocarcinoma (1 paper, 2022). A carcinoma that arises from the lung and is characterized by the presence of malignant glandular epithelial cells. "To explore the effects of DUXAP10 on gefitinib resistance in lung adenocarcinoma cells, we transfected PC9/GR cells with DUXAP10-specific siRNAs to downregulate its expression, and the pcDNA3.1-DUXAP10 vector was transfected into PC9 cells to upregulate its expression." (PMID 36471952, 2022). "Furthermore, we detected the mRNA expression levels of DUXAP10 and OAS2 in 25 lung adenocarcinoma patients before and after gefitinib treatment." (PMID 36471952, 2022).
metastasis (1 paper, 2018). The spread or migration of cancer cells from one part of the body (where they first appeared) to another. "The resutls of Pearson’s chi-square tests revealed that increased DUXAP10 expression were correlated with tumor size (p = 0.012), advanced pathological stage (P = 0.036), and lymph node metastasis (p = 0.023)." (PMID 29374493, 2018).
osteosarcoma (1 paper, 2022). A usually aggressive malignant bone-forming mesenchymal neoplasm, predominantly affecting adolescents and young adults. "Findings from this study indicate that lncRNA DUXAP10 can act as an oncogene in osteosarcoma by binding HuR to up-regulate the expression of SOX18 at a post-transcriptional level, which may provide a new target for OS clinical diagnosis and treatment." (PMID 36053455, 2022).
tumor (15 papers, 2017 to 2025). "The expression of a few previously identified tumor-associated pseudogenes was also found to be significantly dysregulated in GICs, such as DUXAP10." (PMID 34660601, 2021). "In an in vivo BALB/c nude mouse tumor formation study, the mice exhibited larger tumor weights and sizes, which further verified the tumorigenic ability of DUXAP10." (PMID 35186937, 2022). "To confirm the biological function of DUXAP10in vivo, we injected PC9/GR cells transfected with sh-DUXAP10 or empty vector into nude mice to establish a subcutaneous tumor model." (PMID 36471952, 2022). "The higher expression of DUXAP10 in tumor tissues compared with adjacent normal tissues indicates the diagnostic potential of using DUXAP10 to successfully distinguish cancerous tissues from normal tissues." (PMID 35186937, 2022). "In this section, we describe the meaningful medicinal applications of DUXAP10 in numerous tumor types." (PMID 35186937, 2022). "The results showed that the percentage of apoptotic tumor cells was significantly increased in DUXAP10 knockdown cells, which showed the down-regulation of the phosphorylated protein kinase B (p-Akt) and the up-regulation of Cleaved Caspase3 expression levels." (PMID 36053455, 2022). "qRT-PCR analysis confirmed that the expression of DUXAP10 was significantly downregulated in the excised tumor tissues." (PMID 36471952, 2022). "Subsequently, the increased tumor volumes and weights in experimental tumor models further demonstrated the carcinogenicity of DUXAP10." (PMID 35186937, 2022). "More importantly, DUXAP10 was involved in the momentous modulation of tumor progression by stimulating the proliferation of HO8910 and A2780 cells." (PMID 35186937, 2022). "As shown inFigure 6B,C, the tumor weight and volume of the sh-DUXAP10 group were lower than those of the empty vector group." (PMID 36471952, 2022). "Downregulation of DUXAP10 was able to suppress tumor development by inactivating the processes of cell cycle progression, cell proliferation, and metastasis in PC3 and DU145 cells." (PMID 35186937, 2022). "In this study, we observed that the circRNA cZRANB1 and lncRNA DUXAP10 were not only significantly upregulated in tumor tissues, but also higher expressed in blood exosomes of HCC as compared with healthy donors." (PMID 36132143, 2022). "Amongst these tissues, there are 25 normal adjacent tissues that express DUXAP10, and 26 tumor tissues that express DUXAP10." (PMID 30996112, 2019). "It was reported recently that 71.4% patients expressed higher DUXAP10 level than in non-tumor tissues in HCC tissues." (PMID 30996112, 2019). "Knockdown of DUXAP10 exerts tumor-suppressive functions through reducing cell proliferation, growth and invasion." (PMID 29374493, 2018). "Eighteen days after injection, the tumor size in the sh-DUXAP10 group was significantly smaller compared with the control group." (PMID 29374493, 2018). "As shown, qPCR confirmed that the DUXAP10 expression level was lower in the tumor tissues derived from the sh-DUXAP10-transfected cells." (PMID 28779166, 2017). "Statistical analysis revealed that increased DUXAP10 expression were correlated with tumor size (p = 0.022), advanced pathological stage (P<0.001), and lymph node metastasis (p = 0.001)." (PMID 28029651, 2017). "Next, qPCR assays determined that DUXAP10 expression levels were down-regulated in tumor tissues collected from sh-DUXAP10 group compared with control group." (PMID 28029651, 2017). "The results confirmed that DUXAP10 expression is increased in CRC tissues compared with matched non-tumor tissues." (PMID 28779166, 2017). "Increased DUXAP10 in CRC tissues were significantly correlated with larger tumor sizes (P = 0.033), advanced TNM stages (P = 0.016) and lymph node metastasis (P = 0.017)." (PMID 28779166, 2017). "At 15 days post-injection, the tumor growth in the sh-DUXAP10 group was markedly smaller than that in the control group." (PMID 28779166, 2017).